SIRT1 (sirtuin 1)
Diseases named in the same sentence as SIRT1 in open-access papers (continued):
Sharing a sentence is not in itself a finding about the gene and the disease.
osteoporosis (continued). "In 2014, the specific activator of SIRT1, known as SRT3025, was utilized to rescue bone mass in postmenopausal osteoporosis model rats and cost-type atrophic osteoporosis model mice." (PMID 38264287, 2023). "In brief, SIRT1 and SIRT6 can inhibit the development and progression of osteoporosis by resisting oxidative stress, aging and regulating bone metabolism." (PMID 36581622, 2022). "Research has found that among the Sirtuin family consisting of seven Sirtuins (SIRT1-7), SIRT1-SIRT6 play a crucial role in maintaining mitochondrial quality control, which can improve osteoporosis by regulating mitochondrial protein homeostasis, biogenesis, and mitophagy." (PMID 39122452, 2024). "These previous studies, including monogenic bone disorders and knockout mice, confirmed that SIRT1 is a key negative player in osteoclastogenesis and osteoporosis." (PMID 32292498, 2020). "Moreover, Western bolt analysis showed that expression of SIRT1, LC3, and Beclin-1 in osteoblasts increased, while p-AKT and p-mTOR were downregulated in osteoporosis rats with high dose resveratrol treatment." (PMID 31804494, 2019). "The current demonstration of the in vivo efficacy of the SIRT1 agonist SRT1720 on bone mass adds weight to the idea that this Sirtuin is a strong pharmacological target for treating both age-related and post-menopausal osteoporosis." (PMID 28937996, 2017). "Besides, miR-132-3p regulated osteoblast differentiation in osteoporosis by targeting EP300 and SIRT1." (PMID 27556448, 2016). "Our results define a mechanism where Piezo1 integrates mechanical signals into the AMPK/SIRT1/PGC-1α signaling cascade to regulate mechanoadaptive bone formation, highlighting Piezo1 activation as a potential mechanism-based therapeutic strategy for disuse osteoporosis." (PMID 41362723, 2026). "However, the differences in expression of SIRT1, cell cycle regulators, and factors released by aged cells in skeletal muscle tissue of elderly patients with osteoporosis and fragility fracture have not yet been elucidated." (PMID 40564069, 2025). "Therefore, activation of SIRT1 via NMN or nicotinamide riboside (precursors of SIRT1) to increase the NAD+/NADH ratio has become a strategy for the treatment of aging and X-ray induced osteoporosis." (PMID 39199358, 2024). "As miR-217 has been shown to sponge different circRNAs, such as circ-VANGL1 and promote osteoporosis development by downregulating RUNX2 expression, or circRNA_100367 it would be interesting that future studies explore circRNAs/miR-217 interactions and SIRT1 regulation in OA chondrocytes." (PMID 38136977, 2023). "The osteoprotective properties of RSV through the modulation of RANK/RANKL/OPG, SIRT1, Wnt/β-catenin, MAPKs/JNK/ERK, PI3K/AKT, microRNAs, and BMP2 are discussed in this section as the key mechanisms related with bone remodelling and development of osteoporosis." (PMID 37239124, 2023). "Remarkably, we have also described that the intake of this natural mineral-rich water induces signaling through Sirt1/p-AMPK/PGC1α in male and ovariectomized female CD Sprague Dawley rats, fructose-fed or not, which has a beneficial impact upon bone and cartilage and protects against osteoporosis." (PMID 31574967, 2019). "In this study, resveratrol treatment increased SIRT1-induced mitophagy in the DEX-treated osteoblasts via PI3K/Akt/mTOR signaling pathway, which suggested that the PI3K/Akt/mTOR signaling pathway might be a target for osteoporosis therapy." (PMID 31804494, 2019). "Indeed, recent studies with second and third generation SIRT1 agonists have shown even greater promise in preserving bone mass in mice, raising hopes for a possible novel therapeutic for osteoporosis in the not so distant future." (PMID 28542607, 2017).
osteoporosis (continued). "In addition, western blotting analysis showed reduced expression of NOX4 and increased expression of SIRT1 and PTX3 in both experimental groups, although with more pronounced effects in osteoarthritic patients, highlighting lower treatment efficacy in the presence of osteoporosis." (PMID 40956314, 2025). "Another experiment showed that SIRT1 overexpression might enhance FOXO3a transcriptional activity by reducing its acetylation, increasing SOD2 expression, improving osteocyte antioxidant capacity, alleviating oxidative stress-induced bone damage, and countering osteoporosis." (PMID 40678144, 2025). "In the present study, we sought to understand whether the up-regulation of SIRT1 induced by 17β-E2 could promote autophagy via the AMPK-mTOR signaling pathway and inhibit apoptosis via the FOXO3a activation in osteoblasts, and SIRT1 might become a more significant target in osteoporosis treatment." (PMID 34711685, 2021). "Taken together, our findings demonstrated that the up-regulation of SIRT1 induced by 17β-E2 could promote autophagy via the AMPK-mTOR pathway and inhibit apoptosis via the FOXO3a activation in osteoblasts, and SIRT1 might become a more significant target in osteoporosis treatment." (PMID 34711685, 2021). "Moreover, SIRT1 is known as a key negative player in osteoclastogenesis and osteoporosis." (PMID 32292498, 2020).
ischemia (83 papers, 2011 to 2026). A hypoperfusion of the BLOOD through an organ or tissue caused by a PATHOLOGIC CONSTRICTION or obstruction of its BLOOD VESSELS, or an absence of BLOOD CIRCULATION. "EC‐specific knockout of SIRT1 results in severe impairment of postnatal neovascularization in mice, confirming that the loss of SIRT1 inhibits EC sprouting and branching morphogenesis, slowing ischemia‐induced neovascularization." (PMID 38211965, 2024). "In the study of a murine hepatic ischemia/reperfusion injury model, SIRT1 activation alleviated leukocyte infiltration, and higher SIRT1 levels were associated with a lower proinflammatory cytokine profile." (PMID 36982615, 2023). "NAD+ levels have also been associated with the intracellular NAMPT-NAD+-SIRT1 cascade necessary for the improved repair of vasculature post-ischemia." (PMID 37233703, 2023). "Here, we explored the role of smooth muscle SIRT1 in endothelial angiogenesis after ischemia and the underlying mechanisms." (PMID 31938060, 2020). "SIRT1 is activated by resveratrol, the anti-oxidant contained in red wine, and its activation has been linked to protection against ischemia, Huntington disease, Aß toxicity and ageing across species." (PMID 28820880, 2017). "Not to mention, resveratrol has been shown to have protective effect on the BBB during ischemia and in recent years (2003) resveratrol was discovered to be a small molecule activator of Sirtuin 1 (SIRT1), a protein whose activity has been linked to longevity." (PMID 26052537, 2015). "Although the loss of SIRT1/SIRT3 led to a compromised PGC‐1α/PPARα‐mediated transcriptional control of fatty acid oxidation in response to acute ischemia and I/R, their crosstalk in mitochondria plays a more important role in the aging heart during acute ischemia." (PMID 37537789, 2023). "Sirtuin 1 (SIRT1), a member of the nicotinamide adenine dinucleotide-dependent deacetylases, is widely expressed in various tissues and exerts protective effects against cellular stress, especially those associated with ischemia." (PMID 35912113, 2022). "A study has shown that deficiency of SIRT1 in EC or specific knockout of endothelial cell SIRT1 in mice led to a significant reduction of EC sprouting and branching, followed by an impairment of ischemia-induced neovascularization." (PMID 30873415, 2019). "Nicotinamide phosphoribosyltransferase (Nampt, also known as visfatin), the rate-limiting enzyme in mammalian NAD+ biosynthesis, plays several roles in protecting against ischemia, one of which was associated with the Nampt-Sirt1-AMPK neuroprotective signaling pathway." (PMID 30519156, 2018). "However, most of the current research interest is centred on SIRT1 as the central mediator of the defence against oxidative stress and apoptosis caused by ischemia." (PMID 21910904, 2011). "By regulating efficient energy metabolism, ROS, and inflammation during hypoxic-ischemic states, SIRT1 suppresses ischemia-induced brain microvascular endothelial cell (BMEC) apoptosis and promotes neuronal survival." (PMID 39598406, 2024). "Meanwhile, Nampt promotes post-ischemia angiogenesis by modulating Notch signaling through the NAD+-SIRT1 cascade." (PMID 38180752, 2024). "Available literature has shown that SIRT1 downregulation can increase ROS level in acute ischemia and that SIRT1 upregulation can evidently decrease MDA level, increase the levels of GSH-Px and SOD in doxorubicin-induced liver injury." (PMID 38767771, 2024). "Administration of resveratrol, a natural compound found in certain foods, beverages, and supplements, has demonstrated neuroprotection against ischemia in rats via the SIRT1 uncoupling protein 2 (SIRT1-UCP2) pathway." (PMID 38992073, 2024).
ischemia (continued). "SIRT1 inhibition downregulates eNOS expression, whereas activation of SIRT1/eNOS signaling improves blood flow recovery following hindlimb ischemia." (PMID 39598406, 2024). "Post-ischemia, SIRT1 maintains the BBB by inhibiting inflammation, leukocyte adhesion, mtROS generation, and adverse remodeling." (PMID 39598406, 2024). "We also established a gene-editing tool for ischemic stroke therapy using a CRISPR/dCas9 system targeting Sirt1 to protect the brain from the effects of ischemia." (PMID 39239521, 2024). "Recently, it has been shown that SIRT1 negatively regulates angiogenesis, leading to delayed blood flow recovery after ischemia." (PMID 37874367, 2024). "Resveratrol treatment significantly enhanced the intracellular NAD+/NADH ratio, as well as AMPK and SIRT1 activities and, decreased energy ATP requirements during ischemia, consequently suggesting the neuroprotective properties of resveratrol." (PMID 39082038, 2024). "On the other hand, studies have shown that Sirt1 can suppress microRNA-134, which becomes increased shortly after ischemia and has been shown to inhibit Limk1 translation." (PMID 37208551, 2023). "Herein we believed SIRT1 works as an adaptive protection in aging during acute ischemia by increasing its mitochondria distribution and bonding to more SIRT3." (PMID 37537789, 2023). "Our previous research showed compromised SIRT1 nuclear shuttling in the aged hearts, which was worsened under ischemia and I/R stress." (PMID 37537789, 2023). "EC-specific SIRT1 knockout mice have impaired neovascularization and muscle endurance after hindlimb ischemia." (PMID 36852171, 2023). "Sal B exerts its anti-ischemia effects by promoting the M2 polarization of macrophages via the SIRT1/PI3K/AKT pathway." (PMID 35656466, 2022). "Further research is required to elucidate the effects of SIRT1 activity on NAD+ depletion in the setting of ischemia." (PMID 36507335, 2022). "SIRT1 is targeted by miR-200c: in brain microvascular endothelial cells miR-200c inhibition provided protection against in vitro ischemia via SIRT1." (PMID 36466801, 2022). "We suggest that the rapid activation of Sirt1 induced by melatonin, as observed here and in our previous work, supports cell survival during ischemia, and also hastens the formation of autolysosomes, and improves protein recycling." (PMID 36429130, 2022). "For instance, resveratrol has been shown to mimic the effect of ischemic preconditioning, the most powerful endogenous mechanism of protection against ischemia, via SIRT1/UCP2 activation." (PMID 34201106, 2021). "To study the role of SIRT1 in ischemia, we manipulated its level via shRNA and tested ensuing effects on cell death following OGD/R." (PMID 34051800, 2021). "To determine the causal relationship between SIRT1 and blood flow perfusion, we examined the effect of the activation or inhibition of SIRT1 on blood flow recovery after ischemia." (PMID 31938060, 2020). "Conversely, the blood flow recovery was markedly improved, which displayed increased blood flow perfusion on day 3 after ischemia in SIRT1-KO mice (Figure." (PMID 31938060, 2020). "Impaired nucleocytoplasmic shuttling and activation of Sirt1 during ischemic stress exacerbated ischemia-induced MI." (PMID 32908628, 2020). "Since both beneficial and detrimental effects of SIRT1 have been reported, the protective effect of SIRT1 in ischemia remains controversial." (PMID 30416425, 2018).
ischemia (continued). "According to this, in this study we observed that pre-ischemia melatonin administration induced a higher increase in SIRT1 levels, as compared to the post-ischemia treatment in right hippocampus." (PMID 30029514, 2018). "SIRT1 can also reduce stress-induced inflammation and can improve intestinal ischemia/reperfusion-induced ROS accumulation and apoptosis via miR-34a-5p activation, which induces SIRT1-mediated suppression of intestinal ROS accumulation." (PMID 28579962, 2017). "Hippocampal GFAP was also significantly elevated, while Bcl-2 and sirtuin 1 decreased significantly in response to ischemia." (PMID 26594596, 2015). "Compared with the normal group, the expression levels of SIRT1 had significant difference in ischemia group and L-NAME group." (PMID 25114706, 2014). "We here show that the acetylation level of FoxO1, an important target of Sirt1 in mediating cardioprotection, was increased during ischemia and was partially restored by NMN administration." (PMID 24905194, 2014). "Activation of SIRT1 during IPC is known to be protective against ischemia in both the heart and brain." (PMID 24058702, 2013). "Significant research effort is currently being applied to the understanding of the complexities of SIRT1 in the modulation of protection mechanisms following ischemia and the therapeutic possibilities of the enhancement of its activity." (PMID 21910904, 2011). "As a SIRT1 activator, ginsenoside Rc works as a protective mechanism by enhancing energy metabolism and improving cardio- and neuroprotective capacities in both normal and ischemia/reperfusion damage scenarios." (PMID 41567643, 2025). "Furthermore, Tlx, by suppressing oxidative stress and improving the expression of SIRT1, can also contribute to better outcomes after experimental ischemia." (PMID 39596503, 2024). "The authors hypothesized that resveratrol's neuroprotective effects may be via inhibiting phosphodiesterase, and subsequently activating the AMPK/SIRT1 signaling pathway, and lowering ATP energy consumption in neurons during ischemia." (PMID 39082038, 2024). "Recent research implicates micro-endothelial SIRT1 in stroke and ischemia-induced brain damage." (PMID 39598406, 2024). "Moreover, the activation of SIRT1 in the young hearts upon acute ischemia and short‐time I/R stress failed in the aged upon ischemia." (PMID 37537789, 2023). "Sirt1-Sirt3 axis regulates human blood-brain barrier permeability in response to ischemia." (PMID 35286233, 2022). "We further explored whether magnoflorine mediated the autophagy/Sirt1/AMPK pathway following ischemia in rats." (PMID 36124014, 2022). "Since SIRT1 requires NAD+ for enzymatic activity, it may deplete cellular energy and possibly make neurons more susceptible to ischemia and excitotoxicity." (PMID 36507335, 2022). "In brain, visfatin is mainly expressed in neurons but not glia cells and the overexpression of visfatin upon ischemic stress in reduced ischemia-induced cerebral injuries in middle cerebral artery occlusion model through enhancing SIRT1-dependent AMPK activation." (PMID 32015774, 2020). "Knockdown of cZFP609 improved blood flow recovery after hindlimb ischemia in SIRT1-Tg mice." (PMID 31938060, 2020). "Activation of Sirt1 alleviates ischemia through several mechanisms." (PMID 30519156, 2018). "In addition, the described results confirm that high dose of RWPC reduces neovascularisation in mice subjected to hindlimb ischemia via inhibition of NO pathway despite their ability to increase Sirt-1, AMPKα and PGC-1α/β expressions." (PMID 25299185, 2014). "This last study suggests that inhibition of SIRT1 and other sirtuin enzymes may activate Nrf2, conferring neuroprotection to ischemia." (PMID 23730259, 2012).